SNORA20 (small nucleolar RNA, H/ACA box 20)
Synonyms: ACA20
Gene: Small nucleolar RNA gene on chromosome 6 (159,780,250 to 159,780,381, reverse strand). Ensembl gene ENSG00000207392.
Gene Ontology:
Biological process: RNA processing
Cellular component: nucleolus
Homologues: Orthologues: chimpanzee SNORA20 (99% identical), macaque SNORA20 (95% identical), mouse Snora20 (80% identical), rabbit SNORA20 (80% identical), rat Snora20 (79% identical), pig SNORA20 (74% identical). Paralogues in human: SNORA20B (92% identical).
Diseases named in the same sentence as SNORA20 in open-access papers:
SNORA20 is named in the same sentence as 4 diseases in open-access papers, as found by Europe PMC text mining. Sharing a sentence is not in itself a finding about the gene and the disease. The quoted sentences say what the papers report.
glioblastoma (1 paper, 2015). The most malignant astrocytic tumor (WHO grade IV). "Among the ten most upregulated genes, five (SNORA20, SNORA71A, SNORA23, SNORA3, SNORA68) were recently found to be downregulated by HOXA10 in LN18 glioblastoma cells." (PMID 26362268, 2015).
schizophrenia (1 paper, 2019). A major psychotic disorder characterized by abnormalities in the perception or expression of reality. "Although non-coding RNAs such as small nucleolar RNAs (snoRNAs), microRNAs and long non-coding RNAs (LncRNAs), have been studied in disease etiology, the involvement of SNORA38B, SNORA68, SNORA23, SNORA20, and SNORA3A in the pathogenesis of schizophrenia has yet to be reported." (PMID 30967896, 2019).
tumor (1 paper, 2020). "In addition, some genes (MLF1, SNORA20) are associated with carcinogenesis, and are considered as tumor markers." (PMID 33121152, 2020).
SNORA20 also shares sentences with these, for which no sentence is quoted: cancer (1 paper).